PPARG (peroxisome proliferator activated receptor gamma)
Diseases named in the same sentence as PPARG in open-access papers (continued):
Sharing a sentence is not in itself a finding about the gene and the disease.
breast cancer (continued). "Here, we identified a novel PPARγ-mediated mechanism that negatively regulates CXCR4 expression in both epithelial and stromal breast cancer cells." (PMID 27556298, 2016). "For instance, some of the genes enriched in canine iUC samples i.e., PPARG, TBX2, ERBB2, ERBB3 are genes indicative of luminal subtypes of breast cancer in humans." (PMID 26352142, 2015). "With respect to mammary tumour latency, 25% of DMBA Only-treated PPARγ-WTs developed palpable tumours by week 15, whereas this trended toward week 21.5 in DMBA + ROSI-treated PPARγ-WT mice." (PMID 25889730, 2015). "In another study, curcumin stimulates AMPK activation resulting in downregulation of PPARγ in 3T3-L1 cells and in COX-2 in MCF-7 breast cancer cells." (PMID 25295069, 2014). "Interestingly, our results corroborate with the data which reported that exposure of breast cancer cell lines expressing high levels of PPARγ to natural ligands of PPARγ significantly inhibited NHE1 gene expression compared with noncancerous cells or cancer cell lines expressing low levels of PPARγ." (PMID 23431283, 2013). "Dose-response studies showed that treatment with either PPARγ agonist or antagonist significantly inhibited the growth of human MCF-7 and MDA-MB-231 breast cancer cells in culture." (PMID 23431460, 2013). "PPARγ and RAR ligands inhibited human breast cancer cells proliferation, cell invasion, MMP-9 activity and up regulation of TIMP-1 expression." (PMID 24098526, 2013). "Similar studies were conducted to determine the effects of combined γ-tocotrienol treatment with PPARγ agonist rosiglitazone and troglitazone on PI3K/Akt mitogenic signaling in MCF-7 and MDA-MB-231 breast cancer cells." (PMID 23431460, 2013). "Both iodolipids exert apoptotic effects, and our group has demonstrated that 6-IL is present in mammary cancer cells after I2 supplement and is a functional ligand of peroxisome proliferator-activated receptor (PPAR) type gamma (PPARγ)." (PMID 23705792, 2013). "A slight, but insignificant enhancement of the growth inhibitory effects 1–4 μM γ-tocotrienol was observed when combined with a subeffective dose (3.2 μM) of the PPARγ antagonist, T0070907, in MCF-7 breast cancer cells (Bottom)." (PMID 23431460, 2013). "The growth inhibitory effects of 1–4 μM γ-tocotrienol was significantly enhanced when given in combination with a subeffective dose (3.2 μM) of the PPARγ antagonist, GW9662, in MCF-7 breast cancer cells (Top)." (PMID 23431460, 2013). "Combined treatment of γ-tocotrienol with PPARγ antagonists was found to reduced PI3K, phosphorylated PDK-1 (active), and phosphorylated-Akt (active) levels in MCF-7 and MDA-MB-231 breast cancer cells." (PMID 23431460, 2013). "Studies were conducted to characterize the effects of γ-tocotrienol treatment alone and in combination with specific PPARγ agonists and antagonists on the growth and survival of MCF-7 and MDA-MB-231 human breast cancer cells." (PMID 23431460, 2013). "PPARG is shown to be down-regulated in breast cancer in all the patients and FGF2 is shown to be down-regulated in breast cancer in all but one patient in both FF and FFPE sections." (PMID 21059268, 2010). "Three different breast cancer cell lines; MDA-MB-231, MCF-7, and T47D were analyzed for PPARγ expression." (PMID 20650001, 2010). "In contrast, in the rat MNU-mammary cancer model dietary treatment with GW7845, an agonist of PPARγ, significantly reduced tumor incidence, tumor number, and tumor weight." (PMID 19500378, 2009). "The present study was undertaken to assess the effect of rosiglitazone, a PPARγ agonist and an anti-inflammatory agent, on cisplatin induced nephrotoxicity, and its anticancer activity in DMBA induced breast cancer rats." (PMID 19356226, 2009). "Invasion of breast cancer cells, that often express prominent levels of PPARγ, is inhibited by rosiglitazone (RGZ) in a PPARγ-independent manner." (PMID 18261208, 2008).
breast cancer (continued). "Administration of a PPARγ agonist in conjunction with trastuzumab(Herceptin), a humanized monoclonal anti-HER-2/neu antibody used in thetreatment of metastatic and high-risk HER-2/neu+ breast cancer, could alsorepresent a novel combination of targeted therapies." (PMID 19125177, 2008). "In invasive breast cancer, PPARγ mRNA is significantly decreased compared to normal tissues and COX-2 levels have been shown to be upregulated in breast cancer in multiple studies." (PMID 18237383, 2008). "In addition, the GW9662 antagonist enhances the agonist rosiglitazone's inhibitory effect on breast cancer cells rather than rescuing tumor growth, suggesting that PPARγ activation may not be involved in TZD-caused survival and cell growth inhibition." (PMID 18947424, 2008). "Some authors have demonstrated that leptin increase cell proliferation which is an essential element for tumor metastasis, through cell progression in MCF-7 human breast cancer cells with up-regulation of PKC-α, PPARγ and PPARα." (PMID 16504019, 2006). "In this regard, when combined with PPARγ agonists such as troglitazone (TGZ), ATRA synergistically and irreversibly inhibits growth and induces apoptosis in human breast cancer cells." (PMID 15505623, 2004). "Similarly, PPARG can counteract the combined cytotoxic effects of trastuzumab and lapatinib on HER2-positive breast cancer cells." (PMID 40303293, 2025). "Altogether, these data highly suggest that Rosiglitazone, a PPARγ agonist and a known peroxisome proliferator, as previously discussed, could be used to enhance peroxisome activity in MCF-7 breast cancer cells and potentially reduce their stemness profile." (PMID 41373547, 2025). "Our study confirms the class effect of PPARγ agonists and MEK inhibitors in promoting adipogenesis in breast cancer cells, highlighting their potential interchangeability in clinical applications and offering a promising option for patients with treatment-resistant TNBC." (PMID 39273076, 2024). "FAD mediates PPARγ activity and induces apoptotic cell death through the PERK -eIF2α-ATF4-CHOP axis, the upregulation in Nox4 expression, and the production of cytosolic Ca2+ and ROS in breast cancer cells." (PMID 39765861, 2024). "Therefore, our findings showed molecular mechanisms of MMPP by regulating VEGFR2 and PPARγ, and suggested that MMPP has potential to treat breast cancer." (PMID 37942548, 2024). "Therefore, MMPP is ascertained to be a potent anticancer drug for breast cancer by regulating VEGFR2 and PPARγ." (PMID 37942548, 2024). "It is hypothesized that MMPP may exercise its effects on breast cancer by acting on VEGFR2 and PPARγ." (PMID 37942548, 2024). "In the context of breast cancer cells, the activation of Peroxisome Proliferator-Activated Receptor γ (PPARγ) triggers an upregulation of HIF1α expression, and HIF1α, in turn, mediates PPARγ-induced activation of autophagy, thereby promoting the survival of MDA-MB-231 breast cancer cells." (PMID 38315272, 2024). "The increased PPARγ-dependent and decreased NFκB-dependent and ERα-dependent gene transcription resulting from AKR1C3 inhibition is predicted to inhibit breast cancer cell proliferation, making it a potential target for breast cancer treatment." (PMID 38523637, 2024). "Our analysis revealed that the five unique hub genes (PPARG, HIPK2, ZFP36L1, HMGB2 and ALDH1A3) may constitute a gene expression signature specifying a therapeutic response of ERβ1-expressing ERα-positive breast cancer cells to treatment with OHT+ATRA." (PMID 36835157, 2023).
breast cancer (continued). "Briefly, the ER + breast cancer cell lines, T47D and ZR75, were co-transfected with the NNAT promoter-reporter construct, and plasmids that constitutively expressed E2F1, E2F4, NRF1, PPARα/RXR, PPARγ/RXR, or control (pLX304)." (PMID 37400769, 2023). "Very recently, we found that cytoplasmic colocalization of RXRα and PPARγ, as well as cytoplasmic RXRα itself, are independent negative prognosticators in breast cancer patients." (PMID 37509273, 2023). "We found that control, but not PPARγ-OE, populations provided factors that supported the proliferation, measured by Ki67 staining, and, therefore, the expansion of both breast cancer cell models on collagen gels." (PMID 37816052, 2023). "Analysis of the prognostic value related to TR expression showed that patients with breast cancer with low mRNA expression levels of FABP4 (log-rank P = 0.012), ADIPOQ (log-rank P = 0.01), PPARG (log-rank P = 0.00013), and PPARGC1A (log-rank P = 0.02) had worse OS than those with high mRNA levels." (PMID 36114448, 2022). "Likewise with prostate cancer an inverse correlation between PPARγ and ALOX15B expression has been shown in breast cancer." (PMID 36438817, 2022). "Jiang’s team found that the expression of PPARγ in the breast tissues of TNBC patients was significantly lower than that of other subtype patients, and its expression in MDA-MB-231 cells was also significantly lower than that of other breast cancer cell lines." (PMID 36611922, 2022). "A later study, however, showed that while 15d-PGJ2 activates PPRE-mediated transcription, PPARγ is not required for 15d-PGJ2-induced apoptosis in breast cancer cells." (PMID 35954274, 2022). "Taken together, modulation of PPARγ signaling and CREBBP depends on the breast cancer subtype." (PMID 36114448, 2022). "The elevated phosphorylation of PPARγ (pS112) in non-immune-infiltrated tumors suggests a novel immune evasion mechanism in breast cancer characterized by increased PPARγ phosphorylation." (PMID 36139700, 2022). "Breast cancer cases with a TIL Salgado score of >15% showed a significantly decreased overall survival and peritumoral inflammation (according to Klintrup) determined the prognostic value of ER, PR, and PPARγ in BC." (PMID 36230483, 2022). "As our study seems to be one of the first investigating a potential involvement of PPARγ in the anti-carcinogenic effect of MTE in breast cancer, there is a lack of evidence regarding the alteration of cellular pathways." (PMID 35079875, 2022). "Until now, studies investigating a potential association between PPARγ and the anti-carcinogenic effect of MTE on breast cancer cells are lacking." (PMID 35079875, 2022). "Further in vivo study revealed that combined therapy with CUR and CIS inhibited the mammary tumor growth accompanied by increased peroxisome proliferator-activated receptor gamma (PPAR-γ) expression and decreased brain-derived neurotrophic factor (BDNF) expression in mammary tumors." (PMID 35216255, 2022). "We have found that NSAIDs induced PRODH/POX and PPARγ expressions (as demonstrated by Western Blot or immunofluorescence analysis) and cytotoxicity (as demonstrated by MTT, cytometric assay, and DNA biosynthesis assay) in breast cancer MCF7 cells." (PMID 35163433, 2022). "These PPARγ-induced metabolic features are typical in a tumor-supporting stroma, as evidenced by accelerated tumor xenograft growth of MDA-MD-231 breast cancer cells when co-implanted with transgenic fibroblasts overexpressing PPARγ, but not with wild-type fibroblasts." (PMID 33946986, 2021). "This indicates that the PPARγ and RXR agonists can affect EV-mediated cross talk in breast cancer." (PMID 33946403, 2021). "Moreover, selective antagonism of PPARγ with T0070907 inhibited proliferation, invasion, and migration in MDA-MB-231 and MCF-7 breast cancer cells." (PMID 33808259, 2021).
breast cancer (continued). "Within the first hour of incubating an estrogen receptor alpha-positive (ER+) breast cancer cell line, MCF7, in 50 nM of a potent pan-HDAC inhibitor, LBH589, we observed a marked initial accumulation of acetylated PPARγ, despite overall levels of FLAG-tagged PPARγ remaining unchanged." (PMID 34580286, 2021). "Moreover, activation of PPARγ in several cells of the TME, including macrophages and fibroblasts, induces a shift towards less aggressive phenotypes, thus negatively impacting breast cancer progression." (PMID 33352766, 2020). "Indeed, genes commonly down-regulated in both Lats2-CKO PyMT tumors and LATS2L lumB human breast cancers were significantly enriched for “PPAR signaling”, confirming the link between LATS2 and PPARγ activity in both mouse and human tumors." (PMID 30456386, 2018). "We performed bioinformatics analysis of the data from the miRDB, Targetscan, Pictar, and miRanda websets to explore the molecular mechanism of miR-27a as an oncogenic molecule in breast cancer, and found that six genes are overlapped, namely TMEM170B, GPAM, PPAP2B, ST6GALNAC3, EYA1, and PPARG." (PMID 29367600, 2018). "Interestingly, luminal breast cancer patients with low expression of both LATS2 and PPARG displayed impaired overall survival, compared with patients with low LATS2 but high PPARG expression." (PMID 30456386, 2018). "Patients carrying a BRCA1 germline mutation overexpressed VDR (BRCA1mut vs. sporadic: IRS 6.00 vs. IRS 3.00%, p < 0.001), RXR (BRCA1mut vs. sporadic: IRS 6.00 vs. IRS 3.00, p = 0.010) and PPARγ (BRCA1mut vs. sporadic: IRS 2.00 vs. IRS 0.00, p < 0.001) when compared to sporadic breast cancer." (PMID 28427429, 2017). "Recently revealed that PPARγ activation depend on autophagy, since GW9662 was able to prevent the upregulation of Beclin-1 as well as the accumulation of LC3 and MDC labeled vacuoles in breast cancer cells." (PMID 28460464, 2017). "To investigate the role of activated PPARγ in the context of heterotypic signaling working in tumor-stroma interactions, we examined the ability of BRL to reduce CAF-induced effects through CXCR4 axis inhibition in breast cancer cells." (PMID 27556298, 2016). "Therefore, we evaluated PPARγ expression in MCF-7 and MDA-MB-231 breast cancer cells and assessed the effects of BRL on CXCR4 expression at both protein and mRNA levels in both cell lines." (PMID 27556298, 2016). "In breast cancer PPARγ mRNA levels did not correlate with nodal involvement and tumor grade but significantly lower PPARγ levels were seen in large metastatic tumors, patients with local recurrence and poor survival." (PMID 25866814, 2015). "DMBA + ROSI cotreatment did not significantly change PPARγ-WT malignant mammary tumour incidence, but intriguingly, significantly increased malignant mammary tumour incidence by ~8-fold in PPARγ-MG KO mice (p < 0.01)." (PMID 25889730, 2015). "Compared to DMBA Only-treated controls, irrespective of genotype, mammary tumours from mice treated with DMBA + ROSI trended toward increased PPARγ expression accompanied by increased BRCA1 expression (p = 0.09)." (PMID 25889730, 2015). "Since EPA and perhaps its metabolites are also PPARγ agonists the increased expression of BRCA1 mRNAa in the breast cancer xenografts of mice fed the fish-oil supplemented diet could be explained, at least in part, by increased transcription." (PMID 25762631, 2015). "When mammary tumours were analyzed by pathological stage, DMBA Only-treated PPARγ-MG KO mice exhibited a reduction in malignant mammary tumours versus PPARγ-WTs (5 ± 4% vs. 20 ± 8%, respectively; not significant)." (PMID 25889730, 2015). "Moreover, FOXA1, an effector of PPARγ (Varley etal., 2008) and a co-factor of GATA3 in luminal breast cancer (Kong etal., 2011), is a significant co-regulator of both GATA3 and PPARγ in the inferred network." (PMID 25979476, 2015).
breast cancer (continued). "Densitometric analyses of protein expression within mammary tumours revealed surprisingly similar PPARγ protein levels irrespective of genotype or treatment." (PMID 25889730, 2015). "As PPARγ mediates anti-tumor activity in a variety of cancer types, we hypothesized that PTER-ITC could modulate the activity of PPARγ pathway in breast cancer cells and inhibit tumor cell growth." (PMID 25119466, 2014). "Three breast cancer cell lines (MCF-7, MDA-MB-231, T47D) were analyzed for PPARγ expression." (PMID 25119466, 2014). "Our results showed that PPARγ was exported from the cytosol toward the nucleus upon stimulation with PD98059 or U0126 in MDA-MB-231 cells, indicating that MEK1 plays an important role in determining the subcellular localization of PPARγ in human breast cancer." (PMID 23939428, 2013). "Next, we are planning to study the correlation between cytoplasmic PPARγ expression and patient survival further, and develop a MEK-ERK pathway signature in breast cancer cells that could be used for patient selection for treatment with a MEK inhibitor." (PMID 23939428, 2013). "Although a specific PPAR response element has not been identified for these genes, activation of PPARγ provokes a significant decrease in the expression of Blc2 and Surv in mammary tumor cell lines MCF-7 and MDA-MB231." (PMID 23705792, 2013). "Combined treatment of γ-tocotrienol with PPARγ agonists, rosiglitazone, and troglitazone was found to be statistically antagonistic on MCF-7 and MDA-MB-231 breast cancer cell growth, as evidenced by the location of the data point in the isobologram being well above the line defining additive effect." (PMID 23431460, 2013). "However, combined treatment with similar doses of γ-tocotrienol and rosiglitazone or troglitazone resulted in a significant increase in PPARγ and RXR expression in both MCF-7 and MDA-MB-231 breast cancer cell lines." (PMID 23431460, 2013). "Treatment with 0.5–6 μM γ-tocotrienol, 0.4–50 μM PPARγ agonists (rosiglitazone or troglitazone), or 0.4–25 μM PPARγ antagonists (GW9662 or T0070907) alone resulted in a dose-responsive inhibition of MCF-7 and MDA-MB-231 breast cancer proliferation." (PMID 23431460, 2013). "In addition, PPARγ can bind to the RARE as a PPARγ-RXR heterodimer and regulated its expression in lung and breast cancer cell line." (PMID 24098526, 2013). "The ER and PPARγ pathways produce opposite effects on PI3K/AKT signaling, accounting in part, for the divergent responses produced by their cognate ligands in estrogen-dependent human breast cancer cells." (PMID 22538444, 2012). "PPARγ and RXR form a complex with βRARE in the RARβ promoter, and the combination of ligands of PPARγ and RXR was reported to induce RARβ in ATRA-resistant breast cancer cells in the presence of histone deacetylase inhibitor." (PMID 22685453, 2012). "Additionally, there are studies in which PPARγ expression and the effect of ESA on disease pathogenesis have been evaluated in breast cancer cell lines, pre-adipocytes, and colon cancer cell lines." (PMID 21904603, 2011). "Despite these constraints, we found a number of biologically meaningful, differentially expressed genes related to HIST1, HIST2 proteins, and some other such as PPARG, FGF2, APOB, CRHBP, CETP, and RXRG in breast cancer tissue compared to corresponding adjacent normal breast tissue." (PMID 21059268, 2010). "Since these genes have not been identified as PPARγ target genes in breast cancer cells, the results for the first time confirm regulation of NHE1 and MnSOD by PPARγ." (PMID 19958503, 2009). "These cells were more sensitive to inhibition of PPARγ with antagonists such as GW9662 and T0070907, as compared with other types of breast cancer cells or normal mammary epithelial cells (Kourtidis A, Carkner RD, Eifert C, Brosnan MJ, Conklin DS; unpublished data)." (PMID 19298655, 2009).